BBS4 (Bardet-Biedl syndrome 4)
Diseases named in the same sentence as BBS4 in open-access papers:
BBS4 is named in the same sentence as 43 diseases in open-access papers, as found by Europe PMC text mining. Sharing a sentence is not in itself a finding about the gene and the disease. The quoted sentences say what the papers report.
ciliopathy (21 papers, 2010 to 2025). A genetic disorder of the cellular cilia or the cilia anchoring structures, the basal bodies, or of ciliary function. "We then examined the RPE in the mouse model of Bardet-Biedl Syndrome 4 (BBS4), a ciliopathy associated with retinal degeneration in humans, and found that ciliation in BBS4 mutant RPE cells is disrupted early during development." (PMID 37211572, 2023). "This includes Bbs4, an essential component of primary cilia that causes a ciliopathy (Bardet-Biedl syndrome) when disrupted, and PCM1 as shown here." (PMID 20531939, 2010). "Similarly, we cannot ascribe a causal relationship between the ciliopathy documented in our study and the loss of function observed in Bbs4-/- mice." (PMID 24695551, 2014). "BBS4 knockout mice recapitulate many of the human ciliopathy phenotypes, including retinal degeneration." (PMID 37211572, 2023). "Other ciliopathy proteins including BBS1,2,4,6,7,8, NPHP5 and OFD1 also interact with proteasomal components, while loss of BBS4, BBS7 and OFD1 also resulted in a decrease of proteasomal activity." (PMID 29796181, 2018). "Taken together, these findings implicate a ciliopathy gene, BBS4, in the regulation of BDNF signaling through TRKB and suggest its importance in localization of the receptor to the axoneme of primary cilia." (PMID 24867303, 2014). "Our data bring further clarity to the extent of ciliopathy in the Bbs4-/- mouse model of Bardet-Biedl syndrome and implicate ciliopathy as a potential contributing factor to the disease phenotype." (PMID 24695551, 2014). "Bbs4 is encoded by one of the causative genes of Bardet-Biedl syndrome (BBS), an inherited ciliopathy characterized by renal cystic disease, obesity, polydactyly, and diverse neuropsychiatric symptoms." (PMID 24349431, 2013). "However, our findings are consistent with previous studies of other BBSome genetic knockouts (Bbs2–/– and Bbs4–/–), which demonstrate that dysregulated leptin receptor signaling is a key ciliopathy-mediated disruption contributing to obesity in BBS." (PMID 40233116, 2025). "Moreover, they revealed that depletion of the BBIP1 protein also significantly reduces the incorporation of the BBS4 protein into the BBSome complex, leading to an aberrant BBSome complex and ciliopathies." (PMID 37239474, 2023). "Similarly, the loss of BBS4 and OFD1, two ciliopathy-related proteins, decreases localization of proteasomal subunits at the centrosome, causing the accumulation of Sonic Hedgehog and Notch signaling mediators that are normally degraded by UPS." (PMID 35646931, 2022). "Mutations in genes that are known ciliopathy genes such as Bbs4 and Bbs8 do not have an essential role in coordinating lens alignment." (PMID 36456625, 2022). "Inactivation of USP35 in a zebrafish model of BBS4 ciliopathy, rescues different ciliary defects, such as impaired convergent and extension movements during gastrulation, renal tubule convolution and retinal degeneration, thus ameliorating the phenotype(s) of BBS4-depleted animals." (PMID 35646931, 2022). "Some ciliopathy proteins, such as BBS4, CEP290 and OFD1, are constituents of centriolar satellites." (PMID 23110211, 2012). "To examine how ciliopathy protein complexes might function together, we have analyzed double mutants of an allele of the Meckel syndrome (MKS) complex protein MKS1 and the BBSome protein BBS4." (PMID 28291807, 2017). "Bbs4-/- mice are a model of Bardet-Biedl Syndrome (OMIM #209900), a ciliopathy characterized mainly by polydactyly, renal and gonadal malformations and truncal obesity." (PMID 33200981, 2020). "In preliminary experiments, we found no defects in cilia structure or protein localization in zebrafish cep290 and bbs4 Crispr/Cas9 mutants (data not shown) suggesting that for some ciliopathy genes, compensation mechanisms may mask ciliopathy phenotypes." (PMID 29568513, 2018). "Careful analysis revealed that ciliopathy was not a uniform property of the Bbs4-/- mouse brain." (PMID 24695551, 2014).
ciliopathy (continued). "The fact that the reductions in PNC number and ciliopathy observed in the hippocampus and amygdala of Bbs4-/- mice were not generalized to all areas of the brain is an important observation that provides further support for the hypothesis that ciliopathy may contribute to the BBS phenotype." (PMID 24695551, 2014).
Obesity (21 papers, 2011 to 2025). Accumulation of substantial excess body fat. "Multisystem involvement was evident in patients with FREM1 or BBS4 variants (e.g., P12, P13, P25), presenting with bifid nose, skeletal anomalies, obesity, polydactyly, or congenital heart disease (CHD)." (PMID 41288877, 2025). "Disruption of BBS2 is specifically associated with adult obesity whereas BBS4 and BBS6 have been linked to both adult and childhood obesity." (PMID 37064917, 2023). "In mice, loss of Bbs2, Bbs4 and Bbs6 causes hyperphagia, obesity and hyperleptinemia, and hypothalamic neurons of Bbs4−/− mice lack ciliary localization of appetite-regulating G-protein coupled receptors." (PMID 27482817, 2016). "Our data shows that ectopic expression of human BBS4 was able to reduce hyperleptinemia and rescue obesity in Bbs4 deficient mice." (PMID 23554981, 2013). "At around 4 months, Bbs1M390R knock-in, Bbs2 −/−, Bbs4 −/−, Bbs6 −/−, and Bbs7 −/− mice developed obesity characterized by hyperphagia." (PMID 37064917, 2023). "Bbs2, Bbs4, Bbs6, and Bbs12 KOs, as well as a Bbs1M390R/M390R knock-in animals, develop obesity driven by hyperphagia." (PMID 35653384, 2022). "Germline ablation of the Bbs2 and Bbs4 (Bbs2−/− and Bbs4−/−) genes led to hyperphagia-induced obesity, coupled with reduced phosphor-STAT3 levels in the hypothalamus." (PMID 34211092, 2021). "We identified canine phenotypes comparable with Bbs4-null mice including obesity and spermatozoa flagella defects." (PMID 28533336, 2017). "Bbs4-null mice exhibited obesity, retinal degeneration, male infertility, and flagellum defects." (PMID 40801568, 2025). "Furthermore, Bbs2-, Bbs4-, and Bbs6-null mice exhibit high circulating leptin levels at an early age and before the development of obesity." (PMID 37571382, 2023). "In addition to PRA, BBS4-affected Hungarian Puli dogs displayed spermatozoa flagella defects, albeit less severely affected than that observed in Bbs4-null mice, as well as obesity." (PMID 34828377, 2021). "Indeed, Bbs4−/− mice have obesity, retinal degeneration, primary cilia dyskenisia, and lack spermatozoa flagella." (PMID 23554981, 2013). "Interestingly, we observed a difference in weight and onset of obesity in Bbs4−/− mice is also dependent on genetic background." (PMID 23554981, 2013). "The MYO9A gene was in the BBS4 region of chromosome 15q22-q23, which might be important for obesity." (PMID 23241142, 2012). "This missense mutation (G-C) is located in the fifth exon of BBS4, a gene known to cause BBS, a rare human genetic disorder characterized by obesity, retinal dystrophy, renal anomalies, hypogenitalism, polydactyly, and numerous developmental and behavioral defects." (PMID 22219648, 2011). "Thus, the defect in insulin receptor signaling in Bbs4-/- mice is not related to obesity, but rather due to loss of BBS4 protein." (PMID 26103456, 2015). "Other studies have shown that Bbs2-, Bbs4-, and Bbs6-knockout mice are leptin resistant, independent of obesity; and in these models, hypothalamic leptin receptor signaling was impaired." (PMID 40519161, 2025). "Strikingly, the fasting insulin levels of calorie restricted Bbs2-/-, Bbs4-/-, and Bbs6-/- mice are significantly elevated indicating that the hyperinsulinemia associated with BBS is independent of obesity." (PMID 26103456, 2015). "Similarly, obesity should not confound our results, as at this age there are no weight differences in Bbs4−/− and Bbs4+/+ mice." (PMID 31479441, 2019). "Similarly, obesity in BBS has been associated with hyperleptinemia, which occurs due to leptin receptor mislocalization in hypothalamic neurons in the absence of BBS4." (PMID 23554981, 2013).
Bardet-Biedl syndrome (18 papers, 2010 to 2024). A ciliopathy with multisystem involvement. "Necdin binds to BBS4, a protein implicated in the Bardet–Biedl syndrome, and forms a BBS4‐containing multiprotein complex at the centrosomes." (PMID 34338396, 2021). "The sentinel SNP at the second-most significant locus was rs17753687 (P = 8.6 × 10−7), which is an intronic SNP in BBS4, a gene implicated in Bardet–Biedl syndrome." (PMID 29472613, 2018). "In humans, BBS4 is known to cause Bardet–Biedl syndrome which includes a retinitis pigmentosa phenotype." (PMID 28533336, 2017). "On the other hand, we have identified mutations in genes typically associated with multisystem disorders in patients with a very limited phenotype, e.g., BBS4 mutation causing isolated retinal dystrophy instead of Bardet-Biedl syndrome." (PMID 26112015, 2015). "Here we report a role for the Bardet-Biedl Syndrome gene, BBS4, in regulation of BDNF signaling through the TRKB receptor in cultured human cells." (PMID 24867303, 2014). "While the neuron-expressed Nitric oxide synthase 1 (Nos1) protein is well known for its role in neurotransmission, mutations in genes from the Bardet-Biedl syndrome (BBS) family, such as bbs4, result in an autosomal recessive disorder characterized by mental retardation and other severe symptoms." (PMID 28993314, 2017). "In Bardet–Biedl syndrome, TTC8, BBS9, WDPCP, and IFT27 were shared by the two pipelines, and BBS4, BBS7, BBS12, and IFT74 suffered significantly different selective pressures between TG and BG birds." (PMID 35456484, 2022).
retinal degeneration (7 papers, 2013 to 2025). Degeneration of the retina. "Dramatic reduction in blue opsin expression has also been demonstrated in a few other retinal degeneration models, including Bbs4-knockout mice." (PMID 23687432, 2013). "To investigate whether BBS4 plays a role in RPE ciliogenesis and maturation and could contribute to their retinal degeneration, we analyzed RPE in flatmounts from germline Bbs4-null mice at P0 and in age-matched controls using the same approach that we took for our CD1 albino analysis." (PMID 37211572, 2023).
renal cystic disease (4 papers, 2011 to 2020). "It was reported that some proteins known to cause renal cystic disease (NPHP6;BBS1, and BBS4) also localize to the olfactory epithelium (OE), and thatmutations in these proteins can cause anosmia in addition to renal cysticdisease." (PMID 21614130, 2011). "Furthermore, the mutation of proteins (NPHP6; BBS1, and BBS4) in olfactory epithelium can result in anosmia as well as renal cystic disease." (PMID 33274190, 2020).
Anosmia (3 papers, 2011 to 2025). An inability to perceive odors. "Loss of function in the BBS2, BBS4, or BBS8 genes and their requisite proteins has been identified in dogs with progressive retinal atrophy, concurrent with systemic symptoms such as anosmia, weight gain, and renal dysfunction." (PMID 40548244, 2025).
cognitive deficits (3 papers, 2014 to 2024). "BBS4 mutations have been associated with BBS, a well‐known disorder presenting with complex manifestations of cognitive impairment, truncal obesity, postaxial polydactyly, genitourinary malformations in female, and renal abnormalities." (PMID 32945607, 2020). "Considered with data documenting a role of cilia in signal transduction these findings support the conclusion that alterations in cilia structure or neurochemical phenotypes may contribute to the cognitive deficits observed in the Bbs4-/- mouse mode." (PMID 24695551, 2014).
breast carcinoma (2 papers, 2014 to 2021). "Breast cancer-related genes from GAD were also identified as ESR1 interactors, including TP53BP1, SRA1, and BBS4." (PMID 33987091, 2021). "Among the 69 ciliary-associated genes analyzed, seven genes showed a statistically significant decrease in expression in breast cancers (log fold change: DYNC2H1 = -0.66; IFT46 = -1.07; PKD2 = -1.67; NPHP3 = -1.10; BBS2 = -1.51; BBS4 = -0.78; TTC8 = -1.46)." (PMID 24987519, 2014).
male infertility (2 papers, 2013 to 2025). The inability of the male to effect fertilization of an ovum after a specified period of unprotected intercourse. "In the Sdccag8mut/mut spermatid, lacking this region led to the instability of PCM1 and mislocalization of the satellite-associated proteins, CEP131, and BBS4, which could be attributed to observed male infertility, as CEP131 and BBS4 are essential for flagellum biogenesis and male fertility." (PMID 40801568, 2025). "Several satellite genes have been associated with male infertility and sperm flagellum defects in humans and mice, including PCM1, CEP131, BBS4, OFD1, CEP290, CCDC13, etc.." (PMID 40801568, 2025). "To test if the transgene can act to rescue the deletion of the endogenous Bbs4 and reverse the male infertility, we crossed male transgenic mice, BBS4tg to female Bbs4+/− mice." (PMID 23554981, 2013).
Retinal dystrophy (2 papers, 2011 to 2015). Retinal dystrophy is an abnormality of the retina associated with a hereditary process. "Since loss of BBS4 function is known to cause BBS and BBS4 knockout mice show severe retinal dystrophy, this novel missense mutation in BBS4 is likely to be pathologic in the KKESH205 family." (PMID 22219648, 2011). "The new allele we report here genetically separates BBS4 function in the retina versus other tissues, and therefore provides a useful reagent to specifically interrogate BBS4 function in retinal dystrophy." (PMID 22219648, 2011).
Anxiety (1 paper, 2022). Intense feelings of nervousness, tension, or panic often arise in response to interpersonal stresses. "This contradicts data regarding Bbs4−/− mice, which showed increased levels of anxiety as measured by decreased center to total distance ratio in the open-field test and fewer light–dark transitions in the light–dark box test." (PMID 36498834, 2022).
Auditory hallucination (1 paper, 2025). Perception of sounds without auditory stimulus. "Another gene associated with auditory hallucinations is PCM1, which encodes a protein that forms a complex with other members of the DISC1 interactome, including BBS4 and DISC1." (PMID 40943654, 2025).
diabetes (1 paper, 2020). "To minimize confounding effects of diabetes on islet engraftment, we transplanted islets into the eyes of four-month-old Bbs4-/- mice that were obese and glucose intolerant, but not overtly diabetic yet." (PMID 33200981, 2020).
Hydrocephalus (1 paper, 2013). Hydrocephalus is an active distension of the ventricular system of the brain resulting from inadequate passage of CSF from its point of production within the cerebral ventricles to its point of absorption into the systemic circulation. "Of note, all observed mouse BBS phenotypes, including hydrocephalus were rescued in Bbs4 null mice by ectopic expression of human BBS4." (PMID 23554981, 2013).
Hyperglycemia (1 paper, 2020). An increased concentration of glucose in the blood. "Previous work has shown hyperglycemia and elevated circulating insulin levels in Bbs4-/- mice at 4–6 months of age." (PMID 33200981, 2020).
migraine (1 paper, 2025). "Among these genes, the five most significantly associated with migraine were BBS4 (p = 3.60×10−6), PAM (p = 6.50×10−5), MICA (p = 9.60×10−5), BLM (p = 4.35×10−4), and GPATCH4 (p = 7.29×10−4)." (PMID 41261954, 2025). "For migraine with aura, MICA (p = 2.82×10−7), GPATCH4 (p = 2.39×10−5), BBS4 (p = 7.64×10−4), ALMS1 (p = 8.40×10−4), and CCDC180 (p = 3.38×10−3) were the five most significant ones." (PMID 41261954, 2025).
schizophrenia (1 paper, 2024). A major psychotic disorder characterized by abnormalities in the perception or expression of reality. "Moreover, DISC1 and BBS4 have been shown to be required to PCM1 localization as well and are synergistically associated with mental pathologies, such as schizophrenia." (PMID 38961488, 2024).
BBS4 also shares sentences with these, for which no sentence is quoted: genetic disorder (3 papers); Truncal obesity (2); Alagille syndrome (1); Alström syndrome (1); autism (1); Bartter syndrome (1); congenital heart disease (1); Cornelia de Lange syndrome (1); DiGeorge syndrome (1); Down syndrome (1); Fraser syndrome (1); genitopatellar syndrome (1); hearing loss (1); Hyperinsulinemia (1); hypogonadism (1); Lipedema (1); metabolic disorders (1); migraine with aura (1); neurodevelopmental disorder (1); Noonan syndrome (1); renal dysfunction (1); Retinal atrophy (1); retinitis pigmentosa (1); Retinopathy (1); Rod-cone dystrophy (1); type 2 diabetes (1).